HMGCS1 (3-hydroxy-3-methylglutaryl-CoA synthase 1)
Description:
Catalyzes the condensation of acetyl-CoA with acetoacetyl-CoA to form HMG-CoA, which is converted by HMG-CoA reductase (HMGCR) into mevalonate, a precursor for cholesterol synthesis.
Synonyms: HMGCS; CMYO28
Tractability: Small molecule: a structure with a bound ligand is known. Antibody: the Human Protein Atlas places it where antibodies can reach. PROTAC: ubiquitination databases record sites on it; its protein half-life has been measured.
Gene: Protein-coding gene on chromosome 5 (43,287,470 to 43,313,512, reverse strand). Ensembl gene ENSG00000112972.
Subcellular location: Cytoplasm
Subcellular location (Human Protein Atlas): Cytosol; Nucleoplasm; Plasma membrane
Pathways (Reactome):
Metabolism: Activation of gene expression by SREBF (SREBP); Lanosterol biosynthesis; PPARA activates gene expression
Gene Ontology:
Molecular function: protein binding; protein homodimerization activity; hydroxymethylglutaryl-CoA synthase activity; acyltransferase activity
Biological process: acetyl-CoA metabolic process; cholesterol biosynthetic process; farnesyl diphosphate biosynthetic process, mevalonate pathway; lipid metabolic process; geranylgeranyl diphosphate biosynthetic process; isopentenyl diphosphate biosynthetic process, mevalonate pathway; isoprenoid biosynthetic process; zymosterol biosynthetic process
Cellular component: cytosol; nucleoplasm; plasma membrane; cytoplasm
Genetic constraint (gnomAD): Loss-of-function variants: 2 observed, 35.82 expected, observed/expected ratio (o/e) 0.0558, 90% interval 0.022 to 0.18. The synonymous counts are far from expectation, so gnomAD's model fits this gene poorly and the ratio says little. Missense variants: 215 observed, 456.81 expected, observed/expected ratio (o/e) 0.47, 90% interval 0.42 to 0.53. Synonymous variants: 120 observed, 157.83 expected, observed/expected ratio (o/e) 0.76, 90% interval 0.65 to 0.88.
Homologues: Orthologues: chimpanzee HMGCS1 (99% identical), macaque HMGCS1 (99% identical), rabbit HMGCS1 (97% identical), dog HMGCS1 (96% identical), guinea pig HMGCS1 (95% identical), pig HMGCS1 (95% identical), rat Hmgcs1 (95% identical), mouse Hmgcs1 (95% identical), tropical clawed frog hmgcs1 (80% identical), zebrafish hmgcs1 (78% identical), Drosophila melanogaster Hmgs (57% identical), Caenorhabditis elegans hmgs-1 (37% identical). Paralogues in human: HMGCS2 (61% identical).
Diseases named in the same sentence as HMGCS1 in open-access papers:
HMGCS1 is named in the same sentence as 84 diseases in open-access papers, as found by Europe PMC text mining. Sharing a sentence is not in itself a finding about the gene and the disease. The quoted sentences say what the papers report.
breast carcinoma (19 papers, 2015 to 2025). "Moreover, in silico Kaplan-Meier analysis of a public breast cancer dataset revealed that high expression of HMGCS1 was associated with worse relapse-free survival (RFS)." (PMID 32692762, 2020). "Numerous studies have reported that the upregulation or mutation of HMGCS1 stimulates tumor progression by increasing the in vivo tumor growth and lung metastasis of gastric cancer cells and increasing the cancer stem cell fraction and function in breast cancer." (PMID 36835419, 2023). "For instance, the enzyme HMGCS1, which catalyzes the synthesis of HMG-CoA, is upregulated in both luminal and basal breast cancer subtypes and is associated with breast cancer stemness." (PMID 40002245, 2025). "The mevalonate precursor enzyme 3-hydroxy-3-methylglutaryl-CoA synthase 1 (HMGCS1) is overexpressed in breast cancer, and a key mediator of enrichment of breast CSCs." (PMID 37046596, 2023). "Compared to normal tissues, HMGCS1 protein was higher in the primary tissues of breast cancer, colon cancer, and UCEC, but was lower in clear cell RCC (also known as KIRC)." (PMID 34549901, 2022). "HMGCS1 plays a role in breast cancer stem cells, and its downregulation decreased the stem cell fraction of both luminal and basal breast cancer cells." (PMID 34577783, 2021). "Down-regulation of HMGCS1 also decreased the CSC fraction and function in various model systems, suggesting that HMGCS1 is essential for CSC-activities in breast cancer in general." (PMID 32692762, 2020). "Recent data from a meta-analysis suggested that HMGCS1 is one of the candidates involved in forming tumor stem-like breast cancer cells." (PMID 32349352, 2020). "When detailing the mevalonate pathway in breast cancer using a single-cell qPCR, we identified the mevalonate precursor enzyme, HMGCS1, as a specific marker of CSC-enriched subpopulations within both luminal and basal tumour subtypes." (PMID 32692762, 2020). "High levels of HMGCS1 mRNAs are correlated with poor prognosis and lower survival rates in breast cancer patients." (PMID 32349352, 2020). "HMGCR and HMGCS1 have now been identified as targets of miR-140-3p.1 in breast cancer cells; however, their expression was not repressed by miR-140-3p.1 in human chondrocytes, indicating miR-140 isomiRs act in a tissue-specific manner." (PMID 32660984, 2020). "Analysis of the survival curve revealed that the higher mevalonate pathway associated genes (HMGCR, HMGCS1 and INSIG2) levels were correlated with lower survival times for the breast cancer patients." (PMID 31138773, 2019). "Taken together, using meta-analysis that combines gene set and network analysis, we suggested CXCR4, CXCL1 and HMGCS1 as candidates involved in tumor stem-like breast cancer cells." (PMID 26870956, 2016). "Targeting HMGCS1 in combination with fluvastatin is attractive in tumor cells where HMGCS1 is robustly upregulated in response to statin treatment as was the case in the lung and breast cancer cell lines used in our study." (PMID 26353928, 2015). "However, to the best of our knowledge, this is the first study in which such an effect is observed by direct interference with the normal levels of endogenous HMGCR or the upstream HMGCS1 in breast cancer cells." (PMID 39119789, 2025). "Moreover, the mevalonate precursor enzyme HMGCS1 has been identified as a CSC marker in both luminal and basal tumor subtypes of breast cancer, with expression levels strongly linked to high tumor grades." (PMID 37709746, 2023). "Indeed, the mevalonate precursor enzyme HMGCS1 is a marker of CSC enrichment in breast cancer, whereas CD36, the receptor for the palmitic acid, is overexpressed in CD44-positive metastasis-initiating cells in oral squamous cell carcinoma." (PMID 36732018, 2023). "Further, the high HMGCS1 expression level was correlated with poor prognosis in breast cancer." (PMID 34549901, 2022).
breast carcinoma (continued). "HMGCS1 (3-hydroxy-3-methylglutaryl-CoA synthase 1) is a potential regulatory node in the mevalonate pathway, whose up-regulation is a common transcriptional event in cancer stem cell enriched subpopulations of breast cancer cell lines." (PMID 33750388, 2021). "Whilst an in-depth mechanistic study of HMGCS1-mediated transcriptional effects, lies beyond the scope of this article, the evidence strongly suggests, that HMGCS1 has genuine potential as a therapeutic target, especially in aggressive and basal breast cancer populations." (PMID 32692762, 2020). "Taken together, the findings of this study assert that a dysregulated metabolic state is a distinct feature of CSC-enriched luminal and basal breast cancer subtypes and that in particular; the enzyme HMGCS1 is a novel and potential general marker of this enrichment." (PMID 32692762, 2020). "Whilst HMGCS1 is present and functional within luminal subtypes of breast cancer, all the analysis suggests that its effects may be most deliberate and consequential in the basal subtypes." (PMID 32692762, 2020). "Pharmacological inhibition of HMGCS1 could therefore be a superior novel treatment approach for breast cancer patients via additional CSC blocking functions." (PMID 32692762, 2020). "Finally, at the protein level, IHC results showed that the master mevalonate pathway genes, HMGCR and HMGCS1 were also overexpressed in breast cancer tissue." (PMID 31138773, 2019). "The single-cell analytical approach applied to HMGCS1 gene function confirmed the initial transcriptional observations, although the distinct functionality and molecular interaction of this enzyme when present in differing breast cancer subtypes need further studies." (PMID 32692762, 2020). "Using loss‐of‐function experiments, we demonstrated that the expression of two upstream enzymes of this metabolic pathway, HMGCS1 and HMGCR, is crucial for the primary tumorigenesis of breast cancer cells in vivo." (PMID 39119789, 2025). "High expression of HMGCS1 and 3-hydroxy-3-methylglutaryl-coenzyme A reductase (HMGCR) is correlated with poor prognosis in breast cancer." (PMID 37046596, 2023). "In this sense, it has been demonstrated through microarrays and the RT-qPCR gene expression analysis, that cell treatments with HMGCR inhibitors, differentially induces the expression of HMGCR, HMGCS1 and IDI1 genes in breast cancer cell lines." (PMID 35359411, 2022). "Taken together, this study highlights HMGCS1 as a potential gatekeeper for dysregulated mevalonate metabolism important for CSC-features in both luminal and basal breast cancer subtypes." (PMID 32692762, 2020). "Further characterization revealed that fluvastatin-sensitive lung and breast cancer cells stably expressing shRNAs targeting SREBP2 lost the ability to upregulate HMGCR and HMGCS1 in response to fluvastatin treatment." (PMID 26353928, 2015). "SREBP2 knockdown in lung and breast cancer cells completely abrogated the fluvastatin-induced upregulation of sterol-responsive genes HMGCR and HMGCS1." (PMID 26353928, 2015). "The impact of HMGCS1 and HMGCR in different cell parameters has been evaluated in cell culture, further indicating the more penetrant effect of HMGCR in the functional status of breast cancer cells." (PMID 39119789, 2025). "HMGCR, but not HMGCS1, is also important for the extravasation and subsequent fitness of breast cancer cells in the lung parenchyma." (PMID 39119789, 2025).
breast carcinoma (continued). "To exemplify the usefulness of the findings presented here, we focused on breast cancer and demonstrate that targets of bisphosphonates such as FDPS and GGPS1 as well as statin such as HMGCS1 are excellent fitness genes in breast cancer and many hard-to-treat cancers." (PMID 33670680, 2021). "Given the pronounced effect of HMGCS1 gene-silencing on CSC survival and seemingly mevalonate-pathway-independent regulation of HMGCS1, pharmacological inhibition of HMGCS1 may be a superior approach to specifically target CSC in luminal and basal breast cancer subtypes." (PMID 32692762, 2020).
colon cancer (10 papers, 2019 to 2024). "Previous studies have demonstrated that HMGCS1 expression is associated with malignant progression in colon cancer, gastric cancer, hepatocellular carcinoma, cervical cancer and cutaneous squamous cell carcinomas." (PMID 38263056, 2024). "Especially, HMGCS1 is the most central gene is also linked to one of the important colon cancer altered processes, cholesterol metabolism." (PMID 31528309, 2019). "Especially, HMGCS1 as the most central gene among DEGs and with a distinct involvement in colon cancer purposed by previous findings, deserves further exclusive studies." (PMID 31528309, 2019). "In colon cancer cells, dipyridamole augmented the cytotoxicity of the MEK1/2 inhibitor, trametinib, and was used to treat unresectable or metastatic malignant melanomas with BRAF mutations through the dual targeting of the HMGCS1 and MEK pathways." (PMID 38540310, 2024). "HMGCS1 is upregulated and promotes cell proliferation in colon cancer tissues." (PMID 32685503, 2020). "So, one of the mechanisms by which CA impact on metabolism of colon cancer could be through expression alterations of HMGCS1." (PMID 31528309, 2019). "Suppression of HMGCS1 could reduce the proliferation of colon cancer cells." (PMID 32523679, 2020). "Dipyridamole treatment suppresses the HMGCS1 level through inhibition of cleavage of SREBF2 and downregulates the expression of HMGCS1, c-Myc, and cyclin D1 in colon cancer cells." (PMID 32349352, 2020).
lung carcinoma (7 papers, 2011 to 2026). "In lung cancer patients, elevated c-Jun activation, HMGCS1 expression, cholesterol content and PM CHMP4B correlate with reduced anti-PD-1 immunotherapy efficacy." (PMID 42248910, 2026). "Moreover, USP28, SREBF2 and HMGCS1 were significantly upregulated in LSCC compared to LADC in tissue from a cohort of human lung cancer patients." (PMID 37202505, 2023). "Moreover, overexpression of CYP51A1, HMGCS1, and FDFT1 caused an increase in migration/invasion capabilities of cells in vitro, suggesting a positive association between these proteins and invasiveness of lung cancer cells." (PMID 35805888, 2022). "We confirmed the results of iTRAQ by western blotting with protein samples from sensitive and resistant brain and lung cancer cells and demonstrated that NCI677397 markedly increased the expression of FDFT1, HMGCS1, FDPS, and FASN." (PMID 38140768, 2024). "Furthermore, expression of HMGCS1 and FDFT1 was also reduced in lysates from KPLU compared to KPL tumours, providing additional evidence that Usp28 regulates Srebp2 in lung cancer." (PMID 37202505, 2023).
Obesity (7 papers, 2016 to 2024). Accumulation of substantial excess body fat. "HMGCS1 also serves as a crucial molecular connection between obesity, inflammation, type 2 diabetes, and coronary artery calcification." (PMID 39359475, 2024). "3-Hydroxy-3-Methylglutaryl-CoA Synthase 1 (HMGCS1) and Fatty Acid Desaturase (FADS1) where both identified as being overexpressed in obesity and linked to higher risks of developing type 2 diabetes." (PMID 28606124, 2017). "HMGCS1, NSDHL and FDFT1 encode 3-Hydroxy-3-methylglutaryl-CoA synthase, squalene synthase and NAD(P)H sterol dehydrogenase, respectively, which are all key enzymes involved in different steps of cholesterol biosynthesis and some of which are modulated in obesity." (PMID 30068314, 2018). "For example, in an animal model of high-fat-induced obesity, the expression of ACSL1 and HMGCS1 was inhibited in both hamster and zebrafish livers, and steatosis also occurred in the livers of these animals." (PMID 37239994, 2023). "We observed that the addition of cDDGS positively affects the expression of several genes that have been recently proposed as potential targets for the treatment of obesity, diabetes, cardiovascular disease, and Alzheimer’s disease (e.g., FASN, AACS, ALAS1, HMGCS1, and VSIG4)." (PMID 30509175, 2018).
prostate carcinoma (7 papers, 2019 to 2025). A carcinoma that arises from epithelial cells of the prostate gland. "The inhibition of the mevalonate pathway through the knockdown of either HMGCS1 or HMGCR resulted in reduced cell viability in prostate cancer." (PMID 38610991, 2024). "Further, genome-wide expression profiling in normal human prostate stromal cells co-cultured with human prostate cancer cells demonstrated an overexpression of MVA pathway enzymes HMGCS1 and HMGCR." (PMID 35884561, 2022). "HMGCS1 is upregulated in prostate cancer, and the knockdown of this gene inhibits cell viability in 22Rv1 cells." (PMID 33023006, 2020). "Likewise, the metabolic gene HMGCS1 is oncogenic in prostate cancer, and its overexpression significantly stimulates tumor cell growth." (PMID 41468516, 2025). "Genes, such as HMGCS1 and HMGCR, are associated with the proliferation of prostate cancer cell, but these genes may be responsible for the proliferation of BRCA cells." (PMID 31311202, 2019). "HMGCOA: 3-hydroxy-3-methylglutaryl-CoA synthase 1 (HMGCS1) and 3-hydroxy-3-methylglutaryl-CoA reductase (HMGCR) are upregulated in stromal cells around prostate cancer." (PMID 38610991, 2024). "Immunohistochemical analysis of human tissue by way of microarray confirmed that HMGCS1 and HMGCR were overexpressed in prostate cancer stroma, suggesting that their expression may play a role in transition from organ-confined to metastatic disease." (PMID 35884561, 2022). "Similarly, the overexpression of GGPS1, GART, and HMGCS1 reduced the overall survival duration in patients with glioblastoma, ovarian cancer, and endometrial cancer but not in those with prostate cancer." (PMID 33670680, 2021).